SRSF3 (serine and arginine rich splicing factor 3)
Diseases named in the same sentence as SRSF3 in open-access papers (continued):
Sharing a sentence is not in itself a finding about the gene and the disease.
cancer (continued). "Mouse embryos lacking SRSF3 do not form a blastocyst, and more importantly, we and others found that SRSF3 is tumorigenic acting as a proto-oncogene when overexpressed and is frequently upregulated in various types of cancer." (PMID 37193066, 2023). "As a multifunctional RNA-binding protein and splicing factor, auto- and balanced regulatory mechanisms in SRSF3 expression in host cells are essential in maintaining the proper expression level of SRSF3 protein, which is often disrupted in cancers." (PMID 37416784, 2023). "Conceivably, all types of cancers examined to date exhibit increased expression of SRSF3, which is essential for keeping cancer cell proliferation and cell cycle progression." (PMID 37416784, 2023). "SRSF3‐mediated increase in miR‐17/20a levels inhibits the cell cycle inhibitor p21, promoting self‐renewal in normal and cancer cells." (PMID 37306233, 2023). "RNA-binding protein SRSF3 has been ascribed to a number of cellular functions, including as a proto-oncogene or a potential suppressor in many types of cancer." (PMID 36764525, 2023). "In 2010, we discovered that SRSF3 is a proto-oncogene and overexpressed in numerous types of cancers and demonstrated that this overexpression of SRSF3 in cancer cells is critical for cancer cell proliferation and tumor induction and maintenance." (PMID 37416784, 2023). "Since then, more critical roles of SRSF3 have been revealed, including its roles in the development of human diseases and cancers." (PMID 37416784, 2023). "SRSF3 is a proto‐oncogene able to enhance cell cycle progression and cell proliferation in both normal and cancer cells, including CRC." (PMID 37306233, 2023). "We have demonstrated the correlation of expression level of SRSF3 and overall survival across 33 human pan cancer types." (PMID 35494088, 2022). "SRSF3 was also found to be overexpressed in various cancer types, namely, respiratory, gastrointestinal, genitourinary, endocrine, and mesenchymal tissue-derived tumors." (PMID 35494088, 2022). "Our results showed that SRSF3 expression was positively correlated immune cell infiltration, TMB, MSI in certain cancer types, indicating SRSF3 expression to potential value of therapy response." (PMID 35494088, 2022). "We found that the upregulated SRSF3 expression was significantly associated with ACC, ESCA, KIRP, and LIHC cancer." (PMID 35494088, 2022). "The expression pattern and prognostic worth of SRSF3 among pan-cancers were explored through different databases, namely, the TCGA and Kaplan–Meier Plotter." (PMID 35494088, 2022). "Recent studies have identified that high expression of SRSF3 contributes to tumorigenesis by promoting cancer cell proliferation, migration, invasion, and metastasis." (PMID 35501301, 2022). "Our bioinformatic consequences have shown that SRSF3 was overexpressed among 33 human pan-cancer types when comparing with corresponding normal tissues." (PMID 35494088, 2022). "SRSF3 is expressed in various cancers and its high expression correlated to poor survival and disease progression." (PMID 35494088, 2022). "Patients with high SRSF3 expression level in the majority of cancer types indicated a worse prognosis comparing with the low expression groups in the subsequent survival analysis." (PMID 35494088, 2022). "We identified four proteins (p21, NFkB1, MAPK1, and Sirt2) as potential target gene candidates regulated by SRSF3 through cell stress array analysis, correlation analysis, and expression levels between cancer and normal tissues." (PMID 36344491, 2022). "Elucidation of the mechanism of p21 regulation by SRSF3 will provide important clues for cancer treatment strategies." (PMID 36344491, 2022). "The connection between the expression of SRSF3 and the outcome of patients with cancer were identified by utilizing the TCGA database." (PMID 35494088, 2022).
cancer (continued). "SRSF3 is expressed in various cancers and its high expression correlated to poor survival and disease progression, particularly for ACC, KIRP, and UCEC." (PMID 35494088, 2022). "In our study, we conducted and visualized the prognostic values of SRSF3 in human pan-cancer using different databases, namely, the TCGA and Kaplan–Meier Plotter." (PMID 35494088, 2022). "Dysregulation of SRSF3 is correlated with carcinogenesis in pan-cancer and we chose typical cell lines, namely, SW480 and 786-O cells to perform in vitro and in vivo experiments to verify it." (PMID 35494088, 2022). "We analyzed the relevant signal transduction pathways of SRSF3 in 33 tumors through GSEA to identify the pathways that are differentially activated in various malignant tumors when SRSF3 is highly expressed." (PMID 35494088, 2022). "In summary, SRSF3 expression can be considered as a prognostic biomarker in pan-cancer and therapeutic evaluation." (PMID 35494088, 2022). "In our study, a visualized prognostic landscape of SRSF3 in pan-cancer was investigated and the relationship between SRSF3 expression and immune infiltration was also investigated." (PMID 35494088, 2022). "Our results also imply that inhibiting the interaction between SRSF3 and eIF4A1 is a possible therapeutic approach for inducing p21-dependent cellular senescence in cancer cells." (PMID 36344491, 2022). "The results of correlation analysis have shown that SRSF3 expression was clearly related to immune cells infiltration among human pan-cancers and particularly in BRCA and THYM had the highest coefficients values with immune cells infiltration." (PMID 35494088, 2022). "The correlation between the respective expression level of SRSF3 and OS among 33 human pan-cancer types was examined through single variate Cox regression analysis using data obtained from the TCGA database." (PMID 35494088, 2022). "SRSF3 expression was upregulated in pan-cancer tissue compared with normal tissue, which confirmed by immunohistochemistry and its expression indicated poor overall survival and death-specific survival." (PMID 35494088, 2022). "Some of these reported targets are cancer-related and are associated with carcinogenesis (such as SPRY2, SKY and SRSF3), cancer prognosis (such as CNOT6, RECK and GID4) or cancer cell plasticity (such as RMND5A)." (PMID 33804639, 2021). "The overexpression of SRSF3 is observed in different cancers, and the interaction is facilitated by the binding of ORF57 to the N-terminal RNA-recognition motif of SRSF3." (PMID 33530521, 2021). "Cumulative research on SRSF3 provides critical insight into its essential part in maintaining cellular processes, offering potential new targets for anti-cancer therapy." (PMID 33072610, 2020). "Here, we summarize the function of SRSF3-regulated alternative transcripts in cancer cell biology at different stages of tumor development and the regulation of SRSF3 in tumorigenesis." (PMID 32284746, 2020). "Here, we review state-of-the-art research on SRSF3 in terms of its function, expression, and misregulation in human cancers." (PMID 33072610, 2020). "Further study found that the TDP43/SRSF3/PAR3 axis regulated the metastasis of cancer cells, while the TDP43/SRSF3/NUMB axis controlled the proliferation of cancer cells." (PMID 33072610, 2020). "SRSF3 can be considered as a potential molecular switch that regulates many biological processes in cancer cells, enabling sensitization of cancer cells to therapeutic treatments." (PMID 33072610, 2020). "In alternative splicing, most of the isomers produced by SRSF3 have different phenotypes, which are manifested in promoting and suppressing cancer." (PMID 32284746, 2020). "SRSF3 is frequently upregulated in many human tumors and therefore plays a role as an oncogene in various cancer processes." (PMID 32284746, 2020).
cancer (continued). "Other deregulated genes are also described as being cancer-related, including Srsf3, which has a proto-oncogenic function and is frequently upregulated in various types of cancer." (PMID 32793490, 2020). "SRSF3 is frequently upregulated in cancer and displays pro-oncogenic functions, whereas tumors displaying reduced SRSF3 expression exhibited slower growth and higher apoptosis." (PMID 32023846, 2020). "SRSF3 (serine arginine‐rich splicing factor 3) is a well‐known RNA processing protein that is overexpressed in several cancer types and involved in tumor maintenance." (PMID 32536039, 2020). "In this review, we summarize current research on the function and expression regulation of SRSF3 and the misregulation and biological implications of SRSF3 in cancer, as well as its therapeutic potential." (PMID 33072610, 2020). "SRSF3 is a multi-functional protein, and has been found to be involved in various human diseases, including cancers." (PMID 32308565, 2020). "Nevertheless, investigating the molecular mechanisms governing SRSF3-dependent signaling will promisingly reveal new drug candidates and therapeutic targets for cancer treatment." (PMID 33072610, 2020). "Overexpression of SRSF3 in cancer cell lines has been found through database analysis and tissue sample detection." (PMID 32284746, 2020). "Down-regulated splicing factor SRSF3 is known to promote cellular senescence, an important biological process in preventing cancer and contributing to individual aging, via its alternative splicing dependent function in human cells." (PMID 30835716, 2019). "Reversely, elevated SRSF3 expression level is universal in many cancers, which can promote cell growth and maintain the transformation properties of cancer cells." (PMID 30835716, 2019). "In cancer cells, serine/arginine-rich protein (SRSF3) activates exon 10 expression, which favors expression of PKM2." (PMID 29942258, 2018). "Our findings indicate that the PKM splicers of PTBP1, hnRNPA1, and SRSF3 were involved in the maintenance of cancer-specific metabolism and also tumorigenesis." (PMID 30279379, 2018). "At the cellular level, SRSF3 expression is regulated during cell cycle, SRSF3 overexpression in cancer cells enhances cell proliferation and its depletion leads to a cell cycle arrest." (PMID 29741478, 2018). "Serine and arginine rich splicing factor 3 (SRSF3), an SR-rich family protein, has an oncogenic function in various kinds of cancer." (PMID 30279379, 2018). "Depletion of SRSF3 in cancer cells induced G2/M arrest, growth inhibition and apoptosis, while SRSF3 overexpression in rodent fibroblasts induced cell transformation and tumor formation and growth in nude mice." (PMID 30455716, 2018). "In the ASF-4-1 cell line as a normal cell, the expression levels of PTBP1, hnRNPA1, and SRSF3 were lower than those of all cancer cell lines tested." (PMID 30279379, 2018). "Upregulation of hnRNP proteins was documented to impair the autoregulation of SRSF3 splicing and subsequently resulted in imbalanced expression of SRSF3 in various cancers." (PMID 30200638, 2018). "On the other hand, in all cancer cell lines tested and in human fibroblast ASF-4-1 cell line, PTBP1 was fairly expressed, and good expression of hnRNPA1 and SRSF3 was observed in most of the cancer cell lines." (PMID 30279379, 2018). "Taken together, our results demonstrate that SRSF3 confers the malignant characteristics on cancer cells via the SRSF3/miR-1908-5p/NKIRAS2 axis." (PMID 28039456, 2017). "Despite the lack of efficacy to reach minimum safety dosage in our study, theophylline or other methylxanthine derivatives can be a promising lead compound for targeting SRSF3 in anti-cancer drug development." (PMID 29254178, 2017). "Collectively, elevated SRSF3 expression enhanced the anti-apoptotic signature of cancer cells by reprogramming the splicing profiles of related genes." (PMID 27983653, 2016).
cancer (continued). "In the present study, we discovered that cancer cells exhibit decreased inclusion of exon 4 and increased amount of SRSF3, suggesting that autoregulation of SRSF3 is impaired in those cells." (PMID 26416554, 2015). "The new role of SRSF3 in the regulation of HRR pathway provides a mechanism for cancer cells to meet this need." (PMID 26282282, 2015). "SRSF3 inhibition could potentially alter circRNA expression patterns, leading to changes in cell-cycle regulation, apoptosis, and cancer cell proliferation." (PMID 41303368, 2025). "The SRSF3 gene (serine and arginine rich splicing factor 3) has been reported to play a critical role in cell proliferation by promoting the G2/M transition, and preventing the death of apoptotic cells in cancers where it functions as an oncogene." (PMID 38254188, 2024). "However, it would be interesting to study the functional roles of various ratios of SRSF3-FL/SRSF3-TR in the so-called SFSF3 functions of cancer cells." (PMID 38909100, 2024). "However, based on the literature survey, we first decided to check if miR-6741-3p can target SRSF3 as the involvement of SRSF3 in the pathogenesis of various cancers including OSCC has already been reported." (PMID 38781195, 2024). "Given the critical roles of alternative splicing in cancer biology, pharmacologically modulating SRSF3-mediated splicing might be an essential therapeutic strategy." (PMID 38909100, 2024). "Splicing factor SRSF3 is an oncogene and is overexpressed in many cancers, including HNSCC." (PMID 36835286, 2023). "Altogether, although SRSF3 negatively regulates inflammation and innate immune responses, SRSF3 may play double-edged roles in cancer immunotherapy." (PMID 37416784, 2023). "Among the 16 cell cycle‐associated genes analysed, only CDKN1A expression was increased more than 1.5‐fold in SRSF3‐depleted cells, suggesting that the cell proliferation and cell cycle phenotype in human cancer cells was largely mediated through miR‐17a/20a targeting CDKN1A." (PMID 37306233, 2023). "SRSF3 is involved in regulating the expression of genes related to cancer immunotherapy." (PMID 37416784, 2023). "In addition, in KICH and LIHC, SRSF3 is significantly co-expressed with more immune checkpoint genes, indicating that SRSF3 is easier to regulate tumor immune response by regulating immune checkpoint activity in these three malignant tumors." (PMID 35494088, 2022). "Therefore, the genes regulated by SRSF3 were involved in a variety of biological processes of cancer, suggesting that SRSF3 is expected to be a new therapeutic target for CRC." (PMID 35198444, 2022). "Previous studies have shown that SRSF3 expression could be used as a biomarker for cancer diagnosis and prognosis." (PMID 35198444, 2022). "Additionally, the Kaplan–Meier plotter database was conducted so as to evaluate the relationship between SRSF3 expression and prognosis among cancer types." (PMID 35494088, 2022). "As for SRSF3, it has been reported that SRSF3 has great influence on various type of cancers via splicing regulation In addition, dephosphorylated SRSF3 selectively mediates export of methylated mRNAs to the cytoplasm through YTHDC1 binding by association with NXF1." (PMID 35563766, 2022). "The results of SRSF3 were reported systemically in human pan-cancer first by us and it may indicate that SRSF3 may act as an oncogenic driver and an interesting biomarker for tumor monitoring in further research." (PMID 35494088, 2022). "Moreover, early study in nude mice reported that higher expression level of SRSF3 promotes cell immortalization and transformation, which is needed for cancer induction and maintenance." (PMID 35494088, 2022). "In STAD and THYM, the high or low SRSF3 phenotype has enriched signal pathways related to cancer." (PMID 35494088, 2022). "Thus, we further analyzed any potential correlation of mRNA levels between SRSF3 and p21 in eight cancers using TCGA database." (PMID 36344491, 2022).
cancer (continued). "Collectively, these data present that SRSF3 may serve as an oncogene and a potential prognostic biomarker in human 33 pan cancer." (PMID 35494088, 2022). "Additionally, compared with normal tissue, the expression of SRSF3 was much lower in 3 out of 33 pan-cancers, namely, KICH, KIRP, and THCA." (PMID 35494088, 2022). "Additionally, we investigated the potential mechanism of SRSF3 in cancer cell apoptosis in SW480 and 786-O cells." (PMID 35494088, 2022). "Next, to explore whether SRSF3 regulate stemness of BCSCs, we detected cancer stemness after SRSF3 interference by shRNAs in both the MDA-MB-231 and HCC1806 cell lines." (PMID 35504883, 2022). "The high SRSF3 phenotype enriches multiple KEGG pathways related to cancer, such as MESO and OV." (PMID 35494088, 2022). "Oncogene SRSF3 is overexpressed in many cancers, including OSCC." (PMID 36505770, 2022). "Moreover, PTB2 is considered an oncogenic splicing factor that originates the upregulation of the SRSF3 proto-oncogene, and its inhibition affects cancer cell development." (PMID 34683922, 2021). "Another member of this family, SRSF3, has recently been discussed as a target for cancer therapy." (PMID 34281234, 2021). "The latest study identified Srsf3 as a potential cancer treatment target." (PMID 34354569, 2021). "Srsf3 is an extremely important RNA splicing factor that helps to regulate the expression of many important genes and plays a role in the occurrence and development of a variety of cancers." (PMID 34354569, 2021). "The higher expression of SRSF3 was also found in TCGA(the cancer genome atlas) CRC data." (PMID 32308565, 2020). "Given the crucial roles of alternative splicing in cancer biology, pharmacological modulation of SRSF3-mediated splicing may represent an important therapeutic strategy." (PMID 33072610, 2020). "Thus, the aberrant expression of SRSF3 closely relates to the occurrence, development, prognosis, and treatment response of diseases, including cancer." (PMID 33072610, 2020). "As one of the most important SR proteins, SRSF3 has got a lot of attentions, especially in cancer." (PMID 32308565, 2020). "It was found that hnRNP L knockdown reduced the expression of SRSF3 in many cancer cell lines." (PMID 33072610, 2020). "Regarding the splicing factor SRSF3, increased levels are detected in several cancers." (PMID 33321981, 2020). "In this context, it can be hypothesized that overexpression of SRSF3 might confer resistance to cancer cells upon various stresses through the promotion of nuclear location of HSF1 in cooperation with BIS." (PMID 33086735, 2020). "Previous studies have revealed that SRSF3 was upregulated in many kinds of cancers, including CRC." (PMID 32308565, 2020). "Cellular senescence is a cancer prevention mechanism, and SRSF3 could be one of the regulators given SRSF3 is downregulated in multiple senescence models and upregulated in many cancer types." (PMID 30835716, 2019). "We speculated that the alternative splicing of SRSF3 exon 4 may be correlated to alternative splicing of hnRNP L exon 7 to allow the overexpression of both SRSF3 and hnRNP L in cancer cells." (PMID 31828152, 2019). "SRSF3 is a proto-oncogene that is upregulated in various types of cancer, including OSCC." (PMID 31828152, 2019). "What’s more, knockdown of SRSF3 induced cellular senescence while increased SRSF3 expression promoted cancer-related cellular phenotypes further highlighted its regulatory importance in both biological systems, wherein splicing-dependent function of SRSF3 was mainly focused." (PMID 30835716, 2019).